GOLPH3 (golgi phosphoprotein 3)
Diseases named in the same sentence as GOLPH3 in open-access papers (continued):
Sharing a sentence is not in itself a finding about the gene and the disease.
colon cancer (15 papers, 2017 to 2025). "Specifically, in colon cancer, GOLPH3 overexpression has been linked to tumor aggressiveness, metastasis, and resistance to therapy." (PMID 38828452, 2024). "We next investigated the association between GOLPH3 expression and genomic instability in colon cancer patients." (PMID 38828452, 2024). "To evaluate the association between GOLPH3 and colon cancer, we investigated GOLPH3 expression in colon cancer cell lines and tissues." (PMID 35190555, 2022). "Accumulating evidence suggests that GOLPH3 is associated with cancer-related phenotypes and poor prognosis in various solid tumors, including colon cancer." (PMID 35190555, 2022). "It has been shown that GOLPH3 is associated with the development of colon cancer and accounts for chemotherapy resistance." (PMID 35190555, 2022). "The findings suggested that GOLPH3 expression was positively associated with colon cancer cell autophagy." (PMID 35190555, 2022). "Our findings suggest a potential pathway where BPA exposure may influence colon cancer progression through GOLPH3 upregulation, associated with enhanced malignant characteristics in colon cancer cells observed in our in vitro analyses." (PMID 38828452, 2024). "Besides, elevated GOLPH3 expression has been linked with a poor outcome in colon cancer, and is a possible predictor of 5-FU chemosensitivity." (PMID 35756081, 2022). "proved that suppression of the P13K/Akt/mTOR pathway led to a decrease in colon cancer cell proliferation and promoted apoptosis under the effect of Golgi phosphoprotein 3 (GOLPH3)." (PMID 40377005, 2025). "The correlation between GOLPH3 expression and the tumor microenvironment in colon cancer is highly significant." (PMID 38828452, 2024). "Our findings demonstrated that BPA exposure accelerates colon cancer progression by upregulating GOLPH3 expression, consequently exacerbating the malignant characteristics of cancer cells." (PMID 38828452, 2024). "We next investigated the expression pattern of GOLPH3 in colon cancer by analyzing data from various open-access databases containing information on colon cancer patients." (PMID 38828452, 2024). "The CCK8 and colony formation assays revealed that BPA treatment enhanced the proliferative capacity of colon cancer cells, and this effect was significantly attenuated by GOLPH3 knockdown." (PMID 38828452, 2024). "The findings of the present study demonstrate the regulation of 5-FU chemoresistance in colon cancer via the LINC00612/miR-590-3p/GOLPH3 pathway." (PMID 38806777, 2024). "Inhibition of GOLPH3 significantly suppressed the proliferation ability of colon cancer cells, as demonstrated by CCK8 and colony formation assays." (PMID 38828452, 2024). "Our study contributes to a comprehensive understanding of GOLPH3’s role in colon cancer, particularly its network of effects." (PMID 38828452, 2024). "The presence of GOLPH3 in these specific cell types suggests a critical role in regulating the tumor microenvironment, potentially facilitating colon cancer growth and progression." (PMID 38828452, 2024). "Using gene expression data, we investigated the impact of GOLPH3 on this environment within colon cancer." (PMID 38828452, 2024). "This study represents the first investigation, to our knowledge, into the link between BPA and the GOLPH3 gene in colon cancer." (PMID 38828452, 2024). "Supporting the potential significance of GOLPH3 in tumorigenesis, we observed elevated protein levels in colon cancer tissues compared to normal tissues, and its presence across various cell types within the tumor microenvironment." (PMID 38828452, 2024). "This dual mode of action, both genomic and non-genomic, highlights the complex interplay between BPA and estrogen receptor signaling, ultimately leading to GOLPH3 upregulation and contributing to the tumorigenic potential of colon cancer cells." (PMID 38828452, 2024).
colon cancer (continued). "The transwell assay further indicated that GOLPH3 suppression effectively hampered the invasion and migration capacity of colon cancer cells." (PMID 38828452, 2024). "Peripheral membrane phosphoprotein GOLPH3 has been identified as an oncogenic protein in several solid tumors, including colon cancer." (PMID 35682714, 2022). "Our study found that loss of GOLPH3 attenuated the IL-6 induced phosphorylation of STAT3 in colon cancer cells, while the overexpression of GOLPH3 enhanced STAT3 phosphorylation in the presence of IL-6." (PMID 35372504, 2022). "Quantitative analyses of immunohistochemistry (IHC) staining indicated that GOLPH3 levels increased in colon cancer tissue as the clinical-stage advanced and were elevated overall compared with the levels in normal tissue." (PMID 35190555, 2022). "Taken together, these findings showed that GOLPH3 expression levels were correlated with the degree of malignant features in colon cancer." (PMID 35190555, 2022). "In our previous investigations, we established that the overexpression of GOLPH3 promotes the growth, migration, and chemoresistance of colon cancer cells by activating multiple intracellular signal pathways." (PMID 35756081, 2022). "In contrast, the overexpression of GOLPH3 promoted the migratory and invasive ability of colon cancer cells." (PMID 35372504, 2022). "In six of the eight colon cancer cell lines, the levels of GOLPH3 expression were significantly higher than in normal colon epithelium tissue." (PMID 35372504, 2022). "In this work, we demonstrate the role GOLPH3 plays in colon cancer metastasis via the regulation of autophagy and EMT." (PMID 35190555, 2022). "Together, these results reveal that integrin α3 can promote the migration and invasion of colon cancer cells, which phenocopied the effects of GOLPH3." (PMID 35372504, 2022). "Western blotting confirmed that compared with the level in paired controls, the level of Akt phosphorylated at Ser473 was decreased in GOLPH3-overexpressing colon cancer cells, while the opposite effect was observed in GOLPH3-silenced colon cancer cells." (PMID 35190555, 2022). "Results revealed that it played the function of an oncogene and upregulated GOLPH3 expression through sponging miR-450b-5p in colon cancer." (PMID 35756081, 2022). "In summary, this study provides evidence that GOLPH3 is involved in regulating colon cancer cell invasion and migration through the STAT3 pathway and silencing GOLPH3 down-regulates ZEB1 and Integrin α3 expression to prevent CRC metastasis." (PMID 35372504, 2022). "We investigated the levels of EMT-related markers in GOLPH3-overexpressing and -silenced colon cancer cell lines." (PMID 35190555, 2022). "Recent studies have confirmed that the GOLPH3 gene plays the role of an oncogene, and upregulation of GOLPH3 expression promoted colon cancer cell growth, invasion, and chemoresistance." (PMID 35756081, 2022). "Herein, we found that knockdown of GOLPH3 significantly reduced migration and invasion of colon cancer cells, whereas overexpression of GOLPH3 displayed elevated migration and invasion abilities compared to the control groups." (PMID 35372504, 2022). "To further substantiate the role of GOLPH3 in colon cancer metastasis, we used a lentivirus vector to construct stably overexpressed GOLPH3 in HCT116 and HCT8 cell lines." (PMID 35372504, 2022). "Previous studies that found GOLPH3 promotes Akt in colon cancer were performed using the cell lines HCT-116, LoVo, and SW620." (PMID 35190555, 2022). "The role GOLPH3 plays in colon cancer metastasis was analyzed using western blotting, immunohistochemistry, transwell, wound-healing, and zebrafish assays." (PMID 35190555, 2022). "Further studies will provide insights into the therapeutic value of targeting GOLPH3 to control the progression of colon cancer." (PMID 35190555, 2022).
colon cancer (continued). "In the present study, we established GOLPH3-overexpression and -silenced colon cancer cell lines and their corresponding controls; we also established zebrafish models." (PMID 35190555, 2022). "In agreement with previous research, our results revealed that GOLPH3 expression was positively correlated with cancer progression and indicated a poor prognosis for patients with colon cancer." (PMID 35190555, 2022). "Taken together, these results confirmed that knockdown of GOLPH3 significantly decreased the migration ability and invasiveness of colon cancer cells, whereas overexpression of GOLPH3 demonstrated the opposite effects." (PMID 35372504, 2022). "To study the function of GOLPH3 in colon cancer cells migration and invasion, we used two independent siRNAs targeting GOLPH3 to knock down its expression in HCT116 and HCT8 cells lines." (PMID 35372504, 2022). "Western blotting revealed that GOLPH3 was highly expressed in colon cancer cell lines (HCT-8, HT-29, HCT-116, SW480, and LOVO), but barely expressed in normal human colon epithelial cells (NCM460)." (PMID 35190555, 2022). "Through a series of experiments, we found that the expression of GOLPH3 was increased in colon cancer HT29 cells resistant to 5-fluorouracil (5-FU)." (PMID 33680216, 2021). "GOLPH3 can promote tumor cell proliferation in colon cancer through PI3K/Akt/mTOR and Wnt/β-catenin signaling, and its overexpression can be considered an important sign to evaluate the prognosis of CRC." (PMID 33680216, 2021). "Meanwhile, silencing expression of the GOLPH3 gene can reverse the resistance of HT29 colon cancer cells to 5-fluorouracil and cisplatin." (PMID 32454851, 2020). "Recent work has provided further insight into the involvement of GOLPH3 in the resistance of colon cancer cells to chemotherapeutic drugs." (PMID 32023813, 2020). "Specifically, the study of Zhou and coauthors correlated GOLPH3 overexpression with resistance of HT29 colon cancer cells to cisplatin, a commonly used chemotherapeutic drug that targets DNA." (PMID 32023813, 2020). "Studies in human colon cancer lines indicated that upregulation of GOLPH3 promotes proliferation of colon cancer cells and inhibits apoptosis by activating the Wnt signaling pathway and enhancing the expression of β-catenin." (PMID 32023813, 2020). "It is also reported that GOLPH3 overexpression can activate various signaling pathways, promote cell proliferation, inhibit apoptosis, and induce the sensitivity of colon cancer cells to cisplatin and 5-FU." (PMID 32454851, 2020). "Collectively, the present results indicated that TDH can inhibit the proliferation vitality of colon cancer LoVo cells through downregulating GOLPH3 expression and activity of PI3K/AKT/mTOR and Wnt/β-catenin signaling pathways." (PMID 32454851, 2020). "GOLPH3 is overexpressed in colon cancer tissue and colon cancer cell lines." (PMID 39944595, 2025). "Next, we knocked down GOLPH3 to assess its impact on colon cancer cell behavior." (PMID 38828452, 2024). "PSB inhibits GOLPH3 expression and intracellular signaling pathways in colon cancer cells." (PMID 38806777, 2024). "Interestingly, our data revealed upregulated GOLPH3 protein levels in colon cancer tissue compared to normal intestinal epithelium." (PMID 38828452, 2024). "Furthermore, single-cell analysis of data from multiple public databases, including EMTAB8107, GSE108989, GSE139555, GSE146771_10X, GSE136394, and GSE146771, demonstrated GOLPH3 expression across most cell types within the colon cancer microenvironment." (PMID 38828452, 2024). "GOLPH3 facilitates colon cancer metastasis, both in vitro and in vivo." (PMID 35190555, 2022). "We verified the hypothesis that the upregulation of GOLPH3 promotes EMT in colon cancer cells by inducing autophagy, both in vivo and vitro, using chloroquine (CQ), an autophagy inhibitor that blocks the fusion of autophagosomes with lysosomes." (PMID 35190555, 2022).
colon cancer (continued). "In this study, we aimed to investigate whether and how Golgi phosphoprotein 3 (GOLPH3) facilitates colon cancer metastasis via the regulation of autophagy and epithelial–mesenchymal transition (EMT)." (PMID 35190555, 2022). "Collectively, these findings showed that GOLPH3 enhanced migration and invasion in colon cancer." (PMID 35190555, 2022). "Our results also suggested that GOLPH3 promotes colon cancer metastasis." (PMID 35190555, 2022). "Thus, we proposed that GOLPH3 promotes colon cancer progression by enhancing EMT and confirmed this hypothesis via further experiments." (PMID 35190555, 2022). "Western blot was performed on ten Golgi proteins (GBF1, GM130, Golgin97, TGN38, GRASP65, GRASP55, BLZF1, STX3, STX6, and GOLPH3) in small-cell lung cancer (SCLC), leukemia, colon cancer, and GIST cell lines expressing WT-KIT or MT-KIT." (PMID 37704840, 2023). "In summary, our results showed that GOLPH3 inhibits the phosphorylation of Akt to facilitate autophagy, which enhances EMT and promotes metastasis in colon cancer." (PMID 35190555, 2022). "We found that p62 and LC3 II levels were downregulated in GOLPH3-overexpressing colon cancer cell lines, while LC3 I level remained constant in both GOLPH3-overexpressing and -silenced cells compared with the level in their paired controls." (PMID 35190555, 2022). "Overall, we have demonstrated that GOLPH3 induces autophagy and EMT to promote metastasis in colon cancer via the repression of phosphorylation of Akt at Ser473." (PMID 35190555, 2022). "Together, these results demonstrate that GOLPH3 is highly expressed in CRC tissues and colon cancer cell lines." (PMID 35372504, 2022). "Compared with that seen in colon cancer cells cultured in the regular culture solution, the inhibition of autophagy and EMT by GOLPH3 RNAi was counteracted when Akt Ser473 phosphorylation was repressed by MK-2206 2HCl." (PMID 35190555, 2022). "Conversely, depletion of GOLPH3 downregulated the expression of P-gp, pERK1/2 and β-catenin and reversed the resistance of HT29 colon cancer cells to cisplatin." (PMID 32023813, 2020). "The aim of this study was to investigate the effect and mechanism of TDH on human colon cancer LoVo cell proliferation and migration and explore the correlation of TDH treatment with the expression of GOLPH3 and cell signaling pathways in LoVo cells." (PMID 32454851, 2020). "GOLPH3 promotes IL-6 induced STAT3 activation, followed by induction of integrin alpha 3 and ZEB1 transcription, thereby promoting the metastasis and progression of colon cancer." (PMID 39944595, 2025). "To determine whether the ZEB1 and integrin α3 is regulated by STAT3 signaling in colon cancer cells, we used two independent siRNAs to knock down STAT3’s expression and then examined the expression of ZEB1, integrin α3 and GOLPH3 in HCT116 and HCT8 cells." (PMID 35372504, 2022). "GOLPH3 protein levels were consistently and significantly upregulated in four colon cancer tissues compared with the levels in matched, adjacent non-cancerous tissues." (PMID 35190555, 2022). "In summary, GOLPH3 induces autophagy and EMT, promoting metastasis in colon cancer." (PMID 35190555, 2022). "To further explore the role of GOLPH3 in colon cancer progression, we transfected HCT-116 and HT-29 cells with PMSCV-Vector, PMSCV-Vector-GOLPH3, pSuper-Vector, and pSuper-GOLPH3-sh1#/sh2# lentivirus, respectively, to construct stable GOLPH3-overexpression and -silenced cell lines." (PMID 35190555, 2022). "Furthermore, the co-immunoprecipitation assay confirmed that GOLPH3 interacted with p-STAT3 (Tyr705) and total STAT3 in colon cancer cells, which indicates that GOLPH3 might act as a transport protein." (PMID 35372504, 2022).
gastric cancer (12 papers, 2014 to 2024). A primary or metastatic malignant neoplasm involving the stomach. "GOLPH3 shows higher expression levels in advanced stages of gastric cancer and has been linked with lymph node metastasis and worse survival rates." (PMID 37508488, 2023). "Overexpression of GOLPH3 is associated with poor clinical outcome in gastric cancer, non-small-cell lung cancer (NSCLC) and ovarian cancer." (PMID 29534690, 2018). "Furthermore, one study reported that GOLPH3 overexpression is associated with poor clinical outcome in gastric cancers." (PMID 25286393, 2014). "GOLPH3’s role in gastric cancer progression is also explored, specifically its regulation of Golgi membrane trafficking and glycosylation." (PMID 37508488, 2023). "Researchers conducted in vitro experiments to explore the functional role of GOLPH3 in gastric cancer cells." (PMID 37508488, 2023). "Reducing GOLPH3 expression via RNA interference techniques resulted in significant reductions in cell proliferation, migration and invasion—evidence suggesting GOLPH3 is integral for encouraging aggressive behavior of gastric cancer cells." (PMID 37508488, 2023). "These initial findings provide valuable insight into how GOLPH3 contributes to gastric cancer progression." (PMID 37508488, 2023). "According to a study conducted in 2013, GOLPH3 is highly expressed in gastric cancer, with this elevated expression correlated with adverse clinical outcomes such as decreased overall survival and tumor invasion." (PMID 37508488, 2023). "Studies conducted on gastric cancer patients demonstrated that higher GOLPH3 expression levels were related to advanced tumor stages, lymph node metastasis and lower overall survival rates." (PMID 37508488, 2023). "Western blotting analysis showed that GOLPH3, p-mTOR, p-Akt1, p-4EB-P1 and p-p70S6 were also expressed in the gastric cancer, carcinoma-adjacent, and paired normal gastric mucosa groups." (PMID 25286393, 2014). "To investigate the potential molecular mechanism by which GOLPH3 is involved in gastric cancer, we first used immunohistochemistry to locate GOLPH3 expression in different gastric tissues." (PMID 25286393, 2014). "We found that GOLPH3 was primarily localized to the cytoplasm, and it was expressed in gastric cancer, para-carcinoma and paired normal gastric tissues." (PMID 25286393, 2014). "GOLPH3 and phosphorylated Akt/mTOR pathway proteins were more highly expressed in the gastric cancer group than in the para-carcinoma tissue and paired normal mucosa groups." (PMID 25286393, 2014). "Meanwhile, we discovered the relation of GOPLPH3 and Akt/mTOR signaling in gastric cancer to reveal the potential role of GOLPH3 in regulating mTOR-mediated gastric cancer tumorigenesis, invasion and metastasis." (PMID 25286393, 2014). "The study suggests that targeting GOLPH3 may provide a promising avenue for creating therapeutic approaches to treat gastric cancer." (PMID 37508488, 2023). "However, it should be borne in mind that further research and validation are required in order to validate these findings and fully understand GOLPH3’s involvement in gastric cancer progression." (PMID 37508488, 2023). "Overall, this study highlights the role GOLPH3 plays in gastric cancer progression and suggests it may serve as a potential therapeutic target." (PMID 37508488, 2023). "Likewise, miR-134 suppressed cell proliferation by direct binding to the 3′-UTR of GOLPH3 in gastric cancer cells." (PMID 32601379, 2020). "In gastric cancer cells miR-134 suppresses cell proliferation via targeting of GOLPH3." (PMID 29534690, 2018). "Our results suggested that high GOLPH3 expression was significantly related to histological grade (p = 0.015), depth of invasion (p<0.001), lymph node metastasis (p<0.001), and distant metastasis (p = 0.006) in gastric cancer tissues." (PMID 25286393, 2014). "Moreover, GOLPH3 over-expression was observed in gastric cancer tissue and was highly related to gastric cancer invasion and metastasis." (PMID 25286393, 2014).